IGFBP2 (insulin like growth factor binding protein 2)
Description:
Multifunctional protein that plays a critical role in regulating the availability of IGFs such as IGF1 and IGF2 to their receptors and thereby regulates IGF-mediated cellular processes including proliferation, differentiation, and apoptosis in a cell-type specific manner. Functions coordinately with receptor protein tyrosine phosphatase beta/PTPRB and the IGF1 receptor to regulate IGF1-mediated signaling by stimulating the phosphorylation of PTEN leading to its inactivation and AKT1 activation. Plays a positive role in cell migration via interaction with integrin alpha5/ITGA5 through an RGD motif. Additionally, interaction with ITGA5/ITGB1 enhances the adhesion of endothelial progenitor cells to endothelial cells. Upon mitochondrial damage, facilitates apoptosis with ITGA5 of podocytes, and then activates the phosphorylation of focal adhesion kinase (FAK)-mediated mitochondrial injury.
Synonyms: IBP2; IGF-BP53
Tractability: Small molecule: it belongs to a druggable protein family. Antibody: UniProt places it where antibodies can reach, with high confidence; its Gene Ontology location is reachable by antibodies, with high confidence; UniProt predicts a signal peptide or a membrane-spanning region. PROTAC: ubiquitination databases record sites on it; a small molecule that binds it is known.
Target class: Secreted protein
Gene: Protein-coding gene on chromosome 2 (216,632,828 to 216,664,441, forward strand). Ensembl gene ENSG00000115457.
Subcellular location: Secreted
Subcellular location (Human Protein Atlas): Endoplasmic reticulum; Predicted to be secreted
Pathways (Reactome):
Metabolism of proteins: Regulation of Insulin-like Growth Factor (IGF) transport and uptake by Insulin-like Growth Factor Binding Proteins (IGFBPs)
Gene Ontology:
Molecular function: insulin-like growth factor I binding; protein binding; receptor ligand inhibitor activity; insulin-like growth factor II binding; signaling receptor binding; insulin-like growth factor binding
Biological process: osteoblast differentiation; positive regulation of activated T cell proliferation; negative regulation of canonical Wnt signaling pathway; regulation of insulin-like growth factor receptor signaling pathway; cellular response to hormone stimulus; female pregnancy; response to estradiol; response to estrogen; response to glucocorticoid; response to mechanical stimulus; response to nutrient; response to retinoic acid; response to steroid hormone; response to xenobiotic stimulus
Cellular component: extracellular exosome; extracellular region; non-collagenous component of interstitial matrix; apical plasma membrane
Genetic constraint (gnomAD): Loss-of-function variants: 12 observed, 19.83 expected, observed/expected ratio (o/e) 0.61, 90% interval 0.39 to 0.98. The upper end of that interval is the gene's LOEUF score, 0.98, which puts it in group 4 of 6, group 1 being the genes least tolerant of losing a copy. Missense variants: 312 observed, 346.38 expected, observed/expected ratio (o/e) 0.9, 90% interval 0.82 to 0.99. Synonymous variants: 177 observed, 150.08 expected, observed/expected ratio (o/e) 1.18, 90% interval 1.04 to 1.34.
Homologues: Orthologues: chimpanzee IGFBP2 (100% identical), macaque IGFBP2 (99% identical), dog IGFBP2 (90% identical), pig IGFBP2 (88% identical), rat Igfbp2 (82% identical), mouse Igfbp2 (82% identical), guinea pig IGFBP2 (71% identical), tropical clawed frog igfbp2 (57% identical), zebrafish igfbp2a (46% identical), zebrafish igfbp2b (41% identical). Paralogues in human: IGFBP4 (32% identical), IGFBP3 (28% identical), IGFBP1 (26% identical), IGFBP5 (26% identical), IGFBP6 (26% identical).
Diseases named in the same sentence as IGFBP2 in open-access papers:
IGFBP2 is named in the same sentence as 367 diseases in open-access papers, as found by Europe PMC text mining. Sharing a sentence is not in itself a finding about the gene and the disease. The quoted sentences say what the papers report.
glioma (130 papers, 2005 to 2026). A benign or malignant brain and spinal cord tumor that arises from glial cells (astrocytes, oligodendrocytes, ependymal cells). "In glioma, IGFBP2 is closely associated with METTL3-mediated HOTAIRM1 via its m6A binding-domains and positively regulated by HOTAIRM1, thus promoting VM." (PMID 39691597, 2024). "Kaplan-Meier survival analysis revealed that glioma patients with high IGFBP2 expression were associated with shorter survival time than those with low IGFBP2 tumors." (PMID 38012763, 2023). "In a recent meta-analysis, IGFBP2 expression was associated with poor prognosis in several tumors, including glioma, suggesting its potential as a prognostic biomarker in cancer patients." (PMID 37737709, 2023). "IGFBP‐2 has also been delineated as part of a robust 9 gene signature associated with worse outcome for high‐grade glioma patients." (PMID 37212470, 2023). "As a candidate biomarker, the aberrant expression of IGFBP2 was detected in high-grade gliomas and identified as a signature associated with poor prognosis." (PMID 37091145, 2023). "Insulin‐Like Growth Factor Binding Protein 2, encoded by IGFBP2 gene, is highly expressed in GSCs‐high‐risk gliomas." (PMID 36070228, 2022). "IGFBP2 is positively correlated with tumor grades and negatively associated with the prognosis of glioma patients." (PMID 35783254, 2022). "Increased levels of ADAMTS1 lead to an increased cleaved IGFBP2, one of its target genes, which is associated with poor prognosis in gliomas." (PMID 34316702, 2021). "In gliomas, IGFBP2 is considered to be an oncogene that causes glioma progression through integrin/ILK/NF-kB pathway." (PMID 32296458, 2020). "To determine a direct association of IGFBP2 with the mesenchymal feature of gliomas, we first analyzed the expression association of IGFBP2 with the mesenchymal signature of gliomas by using the TCGA-human glioma gene expression database." (PMID 31560714, 2019). "It has been established that enhanced expression of IGFBP-2 is associated with the progression of tumorigenesis in gliomas, prostate cancer and breast cancer." (PMID 28977895, 2017). "Insulin-like growth factor-binding protein 2, a glioma marker linked to poor prognosis, binds to and modulates IGF2R." (PMID 27770278, 2017). "We propose therefore that an unexpected biological consequence of IDH mutations in glioma is to ameliorate patient survival by promoting tumor-suppressor signaling while inhibiting that of oncogenes, particularly IGFBP2." (PMID 27852048, 2017). "Enhanced expression of IGFBP2 is associated with a large number of malignant cancers that include tumors of breast, ovarian, glioma and prostate." (PMID 23767917, 2013). "Elevated expression of IGFBP2 is associated with progression of tumors that include prostate, ovarian, glioma among others." (PMID 23767917, 2013). "In glioma cells (U251MG), microgravity also induces apoptosis by modulating the expression of apoptosis-associated proteins such as p21 and IGFBP-2, which may offer new therapeutic targets for glioma treatment." (PMID 41513600, 2026). "In gliomas, IGFBP2 expression is linked to tumor growth and malignancy." (PMID 40535771, 2025). "In glioma, surprisingly, IGFBP-2 overexpression is associated with PTEN deficiency." (PMID 39138166, 2024). "Finally, increased expression of IGFBP2 is associated with progression in numerous cancers including glioma, ovarian, prostate, pancreatic, and breast cancer." (PMID 37029430, 2023). "In addition, extracellular functions of IGFBP‐2 have been linked to the proliferative and invasive capacity of glioma cells via integrin β1‐mediated activation of ERK phosphorylation and nuclear translocation." (PMID 37212470, 2023). "Furthermore, previous studies have shown that low expression levels of IGFBP2 are associated with a general hyper-methylation phenotype and improved survival in gliomas." (PMID 35992105, 2022).
glioma (continued). "Finally, IGFBP-2 was also identified as critical component of a complex network (IGFBP-2/Integrin/Integrin-Linked Kinase (ILK)/NF-kB) able to drive glioma progression." (PMID 33604294, 2020). "Indeed, high IGFBP-2 levels promote both proliferation and invasion of glioma cells and have been linked to an adverse prognosis in high-grade gliomas." (PMID 33604294, 2020). "Taken together, these results indicate that IDH-mutant glioma patients generally manifest low IGFBP2 expression, which is associated with improved survival independent of IDH status, whereas high IGFBP2 expression results in worse survival than in the IDH-wildtype group." (PMID 27852048, 2017). "Increasing expression of IGFBP2 could associated to poor glioma prognosis as it may play major role in glioma tumour progression." (PMID 29050331, 2017). "There is strong evidence of an association between gliomas and IGFBP-2." (PMID 26217584, 2015). "Importantly, alternative networks such as the signaling pathway integrin/ILK/NF-κB have been recently showed to be linked to IGFBP2 during glioma progression." (PMID 24962328, 2014). "Interestingly, one mechanism by which IGFBP-2 may act is on myeloid cells; in cancer-associated fibroblasts, IGFBP-2 promotes glioma progression through induction of M2 macrophage polarization." (PMID 41226289, 2025). "Moreover, IGF-I and -II, their receptors, and several IGF-binding proteins (IGFBP-2, -3, -4, -5) are overexpressed in glioblastoma compared with normal brain tissue or low-grade glioma; this overexpression is associated with poor prognosis or less favorable responses to therapy." (PMID 36105407, 2022). "Likewise, Phillip and collaborators (2016) further reported that deficient-IGFBP2 glioma cell treatment with IGFBP2 resulted in a rapid increase of lysine-specific demethylase 1 (LSD1) and methylated histones that have been identified as direct targets of LSD1 (H3K9 and H3K27)." (PMID 33498859, 2021). "Insulin-like growth factor binding protein 2 is being evaluated as a potential cancer biomarker as it is a secreted protein that is readily detected in a patients’ plasma; higher levels have repeatedly been associated with disease severity in prostate cancer and gliomas." (PMID 25774149, 2015). "IGFBP-2 also induces vasculogenic mimicry formation in glioma tissue via integrin alpha-5 and β1/RGD binding as adhesion proteins expressed in endothelial cells such as CD144 are upregulated." (PMID 41226289, 2025). "IGFBP-2 is frequently upregulated in gliomas, prostate cancer, and hepatocellular carcinoma, consistent with its basal expression in these organs." (PMID 41226289, 2025). "Functional experiments conducted in U251 cell lines demonstrated that silencing IGFBP2 significantly inhibits proliferation, migration, and invasion, reinforcing its role as a critical driver of glioma malignancy." (PMID 40535771, 2025). "IGFBP2 knockdown suppressed glioma cell proliferation (P < 0.01) and migration (P < 0.001), linking it to tumor aggressiveness." (PMID 40535771, 2025). "In gliomas, IGFBP2 exhibits grade-dependent expression: mRNA overexpression in glioblastoma versus normal tissues predicts poor prognosis, while elevated protein levels in blood/tissue positively correlate with tumor grade." (PMID 40821817, 2025). "Glioma cell proliferation that was promoted by exogenous IGFBP-2-induced integrin/ERK activation was inhibited by anti-integrin β1 antibody as well as knockdown of the protein." (PMID 41226289, 2025). "For instance, studies have shown an upregulation of IGFBP2 in breast and cervical cancers, while downregulation has been noted in glioma, bladder cancer, and rhabdomyosarcoma (RMS)." (PMID 39854135, 2025). "Pre-operative plasma IGFBP-2 levels were quite different between patients with high-grade glioma, low-grade glioma, and healthy individuals." (PMID 39138166, 2024).
glioma (continued). "Migration and invasion inhibitory protein [MIIP, also known as IIp45] was initially identified as a binding partner of insulin-like growth factor-binding protein 2 (IGFBP2) and a negative regulator of cell invasion in glioma." (PMID 38245780, 2024). "Insulin-like growth factor-binding protein 2 (IBP2) is considered to be an oncogene and it has been proposed as a potential biomarker in various cancers including ovarian, glioma, prostate, colorectal, pancreatic, breast, and liver." (PMID 38172678, 2024). "The level of IGFBP-2 in tumor tissue and plasma of patients with early glioma has been significantly increased." (PMID 39138166, 2024). "In particular, a direct interaction between IGFBP2 and ITGA5 has been observed in glioma cells, and this association is required for IGFBP2-regualted cell mobility." (PMID 38918360, 2024). "Single-cell RNA-seq analysis of HRGs, including LOX, CP, and IGFBP2, was conducted across three distinct glioma datasets." (PMID 38339384, 2024). "Further examination of the Glioma GSE131928 Smartseq2 dataset revealed that IGFBP2 was also expressed in AC-like malignant and NPC-like malignant cells." (PMID 38339384, 2024). "IGFBP2 expression was connected to worse prognosis in glioma, colorectal cancer, lung cancer and even gastric cancer." (PMID 38206646, 2024). "It has been proven that cells with high expression of IGFBP2 tend to aggregate in the vicinity of focal necrotic regions within gliomas, which indicates an important role in hypoxia-related pathways." (PMID 38339384, 2024). "Our findings, consistent with bioinformatics analysis, demonstrate significant upregulation of IGFBP-2 in high-grade glioma tissue samples." (PMID 39138166, 2024). "In the CGGA (Chinese Glioma Genome Atlas) database, we observed a significant upregulation of IGFBP-2 expression levels with the increasing WHO grading of gliomas." (PMID 39138166, 2024). "Previous studies have shown that overexpression of IGFBP-2 promotes glioma cell migration and invasion through activation of matrix metalloproteinase 2 protein and integrin pathways." (PMID 39138166, 2024). "Insulin-like growth factor binding protein 2 (IGFBP2) holds significant importance as a glioma oncogene acting as a central component in several oncogenic signaling pathways." (PMID 38339384, 2024). "In glioma and melanoma, IGFBP2 facilitates the nuclear accumulation of EGFR, thereby activating STAT3." (PMID 38918360, 2024). "IGFBP2 has been shown to play oncogenic and pro-migration roles in numerous types of cancer, including glioma, breast, liver, leukemia, gastric, and bladder." (PMID 37029430, 2023). "IGFBP2 regulates glioma progression by activating EGFR-STAT3 signaling and promoting cell proliferation and chemoresistance via the integrin β1-ERK pathway, whereas IGFBP3-STAT1 activation is associated with neoplastic cell invasion and poor patient outcomes." (PMID 36949068, 2023). "Elevated levels are recapitulated in high grade glioma tissue biopsies and plasma samples in which poor clinical outcome potentiates harnessing IGFBP‐2 as outcome predictor and biomarker." (PMID 37212470, 2023). "Several studies have validated IGFBP2’s possible roles in glioma initiation, proliferation, invasion, and chemoresistance to temozolomide." (PMID 37091145, 2023). "While the oncogenic role of IGFBP2 has been established in various tumor types, including breast, ovarian, glioma and prostate tumors, its specific mechanisms and involvement in HCC have remained elusive." (PMID 37957694, 2023). "Mechanistically, HOTAIRM1 promotes VM formation mediated by METTL3 in glioma progression via regulating IGFBP2 expression." (PMID 38012763, 2023). "Survival curves for four model genes (ABCC3, EMP3, AL161787.1, and IGFBP2) highlighted IGFBP2 as a significant marker of decreased survival outcomes in glioma patients." (PMID 37928523, 2023).
glioma (continued). "IGFBP2 is one of the most common and abundantly expressed IGFBPs in human cancers, which was found to be highly expressed in glioma, cervical cancer, prostate cancer, breast cancer, lung cancer, and other cancers." (PMID 37088808, 2023). "In glioma, IGFBP2 forms a complex with the EGFR leading to EGFR accumulation inside the nucleus and induction of STAT3 transactivation." (PMID 37029430, 2023). "Results revealed that in comparison with healthy controls, IGFBP2 presented up-regulation in glioma tissues, and had higher level in high-grade glioma tissues than that in low-grade glioma tissues." (PMID 38012763, 2023). "In summary, our data demonstrate that HOTAIRM1 facilitates METTL3-mediated VM formation in glioma via up-regulating IGFBP2 expression (graphical abstract)." (PMID 38012763, 2023). "Mechanistic studies show that IGFBP2 stimulates glioma cell VM formation via CD144 and MMP2 up-regulation." (PMID 38012763, 2023). "Insulin-like growth factor binding protein 2 (IGFBP2) exerts a crucial influence on glioma occurrence and development." (PMID 38012763, 2023). "Future in vitro and in vivo experiments are also necessary to validate the specific tumorigenic and immunogenic mechanisms of IGFBP2 in gliomas and advance glioma research." (PMID 37928523, 2023). "HOTAIRM1, post-transcriptionally stabilized by METTL3, promotes VM formation in glioma via up-regulating IGFBP2 expression, which provides a new direction for glioma therapy." (PMID 38012763, 2023). "Neutralizing antibodies against IGFBP2 blocked glioma cell growth in vitro and in vivo, demonstrating the importance of IGFBPs in these tumors." (PMID 37029430, 2023). "Subsequently, RIP assay illustrated that both IGFBP2 and HOTAIRM1 were markedly enriched in immunoprecipitation through bio-HOTAIRM1 beads rather than control, supporting the binding relation of IGFBP2 with HOTAIRM1 in glioma cells." (PMID 38012763, 2023). "Other miRNAs described as targeting IGFBP-2 in glioma cell models, decreasing cell migration, invasion and survival, include miR-204-3p and miR-302b." (PMID 35597813, 2022). "The expression level of IGFBP2 was further compared between the glioma sample and the healthy control sample, it was found that IGFBP2 was significantly overexpressed in the cancer tissue." (PMID 36110851, 2022). "Insulin-like growth factor binding protein 2 (IGFBP2) is an oncogenic protein involved in the development and progression of various cancers, such as glioma, breast, lung and prostate cancers." (PMID 35328346, 2022). "In papillary thyroid carcinoma (PTC), the most common form of thyroid cancer, IGFBP-5 expression is targeted by miR-204-5p, in contrast with the alternate precursor product, miR-204-3p, which was noted earlier as targeting IGFBP-2 in glioma." (PMID 35597813, 2022). "Although a previous meta‐analysis study assessed the connection between IGFBP2 expression and survival in glioma patients, its research score is relatively limited." (PMID 35546443, 2022). "Several studies related to fields indicated high IGFBP2 expression is correlated with worse prognosis for glioma patients." (PMID 35546443, 2022). "Upregulation of IGFBP2 expression was associated with angiogenic mimetic (VM) formation, leading to resistance to anti-VEGF therapy in glioma and had a significant immunosuppressive activity in GBM, which was negatively associated with patient survival." (PMID 35992105, 2022). "In glioma cells IGFBP-2 is well known to act as an oncogene and its increased expression is associated with poor prognosis of GBM." (PMID 35597813, 2022). "We randomly selected one gene from this signature, IGFBP2, and explored its important value in gliomas." (PMID 36110851, 2022). "Next, we randomly selected one gene from this signature, IGFBP2, and explored its important value in gliomas." (PMID 36110851, 2022). "The meta‐analysis showed that high IGFBP2 expression is an indicator of poor prognosis in glioma patients." (PMID 35546443, 2022).